HOXB7 (homeobox B7)
Diseases named in the same sentence as HOXB7 in open-access papers (continued):
Sharing a sentence is not in itself a finding about the gene and the disease.
triple-negative breast carcinoma (1 paper, 2021). An invasive breast carcinoma which is negative for expression of estrogen receptor (ER), progesterone receptor (PR), and human epidermal growth factor receptor 2 (HER2). "The role of HOXB7 was also addressed in triple-negative breast cancer (TNBC) basal B cell line MDA-MB-231." (PMID 34680970, 2021). "We then investigate whether HOXB7 overexpression may have an impact on the methylation of E-cadherin in MDA-MB-468 cells, as reported recently for other triple-negative breast cancer cells." (PMID 34680970, 2021).
tumor (68 papers, 2006 to 2025). "As a key member of the HOX gene family, HOXB7 expression is upregulated in various malignant tumors and is associated with advanced-stage cancer, metastasis, tumor proliferation, and poor patient survival." (PMID 41040515, 2025). "HOXB7 has been found to be overexpressed in a number of tumor tissues and is a valuable early diagnostic and prognostic marker." (PMID 40657360, 2025). "In LUAD, we observed a robust positive correlation between HOXB7 and macrophages M0 and M1, suggesting an association with tumor inhibition." (PMID 39980564, 2025). "The combination therapy was proposed in this study, and HOXB7 silencing associated with TMX showed controlled tumor growth and reduction in immuno- and hepatotoxicity." (PMID 39458966, 2024). "Recent studies have confirmed that HOXB7 is associated with tumor cell invasiveness and proliferation and clinicopathological features." (PMID 37534217, 2023). "The overexpression of HOXB7 promotes metastasis by inducing tumor-associated macrophage (TAM) recruitment." (PMID 34617205, 2022). "Our findings revealed that overexpression of HOXB7 was associates with tumour aggressiveness and unfavourable prognosis by serving a novel prognostic biomarker in HNSCC." (PMID 34303375, 2021). "The association between HOXB7 expression detected by immunohistochemisty and tumor regression grade (TRG) and long‐term survival was analyzed in 143 ESCC patients who underwent neoadjuvant chemotherapy." (PMID 31568655, 2020). "Our results confirmed HOXB7 as an independent significant risk factor for tumor recurrence and survival after curative resection, and it was in accordance with one recently study." (PMID 28454092, 2017). "Statistical analysis showed that higher expression of HOXB7 in HCC tissue was positively associated with tumor size (P = 0.043), differentiation degree (P = 0.008), vascular invasion (P = 0.012) and TNM stage of HCC (P = 0.029)." (PMID 28646927, 2017). "In colorectal cancer, the protein encoded by HOXB7 was considered as a prognostic factor and mediator of tumor development and progression." (PMID 24088503, 2013). "The role of HOXB7 extends beyond its influence on tumor-associated macrophages (TAMs)." (PMID 39980564, 2025). "Moreover, upregulated expression of HOXB7 was significantly associated with pathological grade and tumor stage." (PMID 41040515, 2025). "Moreover, previous studies have shown that abnormally elevated HOXB7 expression was significantly associated with tumor size, cervical lymph node metastasis, malignancy, and etc.." (PMID 34303375, 2021). "HOXB7, a typical transcription regulator, encodes a homologous protein which is not only related to the normal development and differentiation of cells or organs, but also abnormal highly expressed in tumor cells or tissues, and participates in tumor initiated and progression." (PMID 34303375, 2021). "Furthermore, HoxB7 is reported to be a key factor for the tumor-associated angiogenic switch." (PMID 32784646, 2020). "In our study, through the difference analysis of mRNA data of the HNSCC tumor and normal group in the TCGA database, it was found that HOXB7 and HOXB9, located on the same chromosome of HOXB-AS4, were significantly different." (PMID 40657360, 2025). "In xenograft tumor experiments, HOXB7 knockdown significantly reduced tumor growth and Ki67 expression These results support an oncogenic role for HOXB7 in BC cell proliferation." (PMID 41040515, 2025). "Western blot analysis of tumor tissues showed that HOXB7 knockdown led to downregulation and decreased phosphorylation of several key components in the H-Ras/MEK/ERK signaling pathway, including H-Ras, RAF1, p-MEK, and p-ERK." (PMID 41040515, 2025). "HOXB7 was significantly upregulated in BC tissues and cell lines, correlating with advanced tumor stage and poor overall survival." (PMID 41040515, 2025).
tumor (continued). "For example, in prostate cancer (PCa), HOXB7 expression is significantly higher in tumor tissue compared with normal tissue and is strongly correlated with the Gleason score and Tumor Node Metastasis (TNM) stage." (PMID 41040515, 2025). "Further stratification by tumor stage and lymph node metastasis status demonstrated that HOXB7 expression was significantly correlated with tumor progression, showing increased levels in advanced stages and in patients with lymph node involvement." (PMID 41040515, 2025). "HOXB7 that can induce activation of MAPK/ERK pathway which promotes tumor progression is also upregulated in MDS-MSC." (PMID 38254070, 2024). "HOXB7 plays an important role in multiple processes related to tumor formation and progression, including angiogenesis, proliferation, transformation, invasion, and metastasis." (PMID 36718148, 2023). "The expression levels of CDK1, SPC24, and HOXB7 were significantly higher in tumor tissues than in normal tissues." (PMID 36718148, 2023). "The tumor-promoting and metastatic ability of HOXB7 were validated in a xenograft tumor model and bioluminescence imaging, respectively." (PMID 34617205, 2022). "And a xenograft tumor model was established in nude mice to assess the role of HOXB7 in tumor growth." (PMID 34303375, 2021). "Immunohistochemical staining of tumor samples showed that the positive staining of stem cell markers in HOXB7 knockdown cell samples was significantly reduced compared with the control." (PMID 34303375, 2021). "Significantly higher abundance of HOXB7 mRNA was observed in HNSCC samples compared to their non-tumor counterparts." (PMID 34303375, 2021). "This is a strong indication that the HOXB7 role in tumor progression is dependent on the cellular genetic background, especially concerning the HER2 profile and ECM interactions." (PMID 34063128, 2021). "Bioinformatics analysis supports that HOXB7 participates in the regulation of tumor malignant phenotype and can be used as a therapeutic target for small molecule compounds." (PMID 34303375, 2021). "Together, these findings suggested that HOXB7 was critically involved in tumour overgrowth of HNSCC." (PMID 34303375, 2021). "After euthanasia, the tumor tissues were excised, and their expression of HOXB7 was determined by RT-qPCR." (PMID 33330444, 2020). "As expected, YAP/TAZ was mainly localized to nuclei of cultured mouse tumor cells (Hoxb7-Cre;Lats1fl/+;Lats2fl/fl)." (PMID 32960816, 2020). "Four different pLKO.1-shTAZ lentiviruses were constructed and transduced into tumor cells (Hoxb7-Cre;Lats1fl/+;Lats2fl/fl)." (PMID 32960816, 2020). "The prognostic DEmiRNA, hsa-miR-337-3p targeting one DEmRNA (AMOT, a witnessed oncogene in OSCC), has been implicated to target AMOT, HOXB7, MMP-14, PTEN and acted as a tumor suppressor through sponging oncogene." (PMID 31141819, 2019). "A xenograft tumor model was established in nude mice to assess the role of HOXB7 in tumor growth and lung metastasis." (PMID 30664713, 2019). "All these findings suggest that MMP2, MMP9, VEGF, and IL8 are critical during HOXB7-promoted angiogenesis, which in turn supports tumor growth and metastasis." (PMID 30664713, 2019). "HOXB7 overexpression contributes to tumorigenesis, tumor migration, and invasion through the induction of EMT in epithelial cells." (PMID 31013831, 2019). "In vitro depletion or overexpression experiments showed that HOXB7 promotes tumor cell proliferation, migration, and invasion in HCC." (PMID 28454092, 2017). "Further assessment revealed that HOXB7 expression promoted tumor growth and resulted in larger tumors (P < 0.05)." (PMID 28646927, 2017). "A positive correlation between HOXB7 expression and multiple tumors, satellite lesions, vascular invasion, and more advanced tumor stage indicated that HOXB7-positive tumor cells have a more aggressive phenotype." (PMID 28454092, 2017).
tumor (continued). "As a member of HOX gene family, the roles of HOXB7 in tumorigenesis have been reported in several tumor types, including leukemias, ovarian carcinoma, breast cancer, gastric cancer and colorectal cancer." (PMID 28454092, 2017). "HOXB7 protein was predominantly detected in the nuclei of tumor cells, although cytoplasmic staining was also observed." (PMID 28454092, 2017). "Meanwhile, we also found that human tumor tissues with high HOXB7 expression showed higher bFGF expression." (PMID 28454092, 2017). "Our in vivo results show that over-expression of HOXB7 significantly accelerates subcutaneous tumor growth and increases the number of lung metastases." (PMID 27901487, 2017). "HOXB7 positive staining was also correlated with tumor grade, as 83.9% of Grade IV tumors showed HOXB7 staining while only 15.3% of Grade I GC tumors were positive (P<0.05)." (PMID 27901487, 2017). "HOXB7 positivity was also correlated with tumor size, as 72.8% of tumors from GC patients (size ≥5cm) showed positive HOXB7 staining, compared with 50.7% of GC tumors < 5cm (P<0.05)." (PMID 27901487, 2017). "Recently, it was reported that HOXB7 plays a dual role in HER2 positive breast cancer progression by delaying tumor formation, but promoting lung metastasis." (PMID 27901487, 2017). "Conversely, tumor weights were significantly greater in the HOXB7 overexpression group (MHCC97L-HOXB7 pCDNA3) than in controls (2.083±0.581 g vs. 1.033±0.476 g, P<0.01) and the lung metastatic ratio was significantly increased (30% vs. 0%, P<0.01)." (PMID 28454092, 2017). "In cohort II, the high expression of HOXB7 protein was detected in 61 of 103 (59.2%) cases of tumor tissue samples." (PMID 26076456, 2015). "Enforced expression of miR-196b leads to reduced cell growth, clonogenicity, migration and invasion in vitro, as well as reduced tumor angiogenesis and tumor cell proliferation in vivo via regulating the Homeobox B7-vascular endothelial growth factor axis." (PMID 25525411, 2014). "Studies have shown that HOXB7 plays an important role in transformation, proliferation, and survival of tumor cells." (PMID 24641834, 2014). "Elevated expression of HOXB7 protein in the tumor was correlated with different tumors of different diameters (P = 0.043), levels of differentiation (P = 0.009), TNM stage (P = 0.008), and lymph node status (P = 0.015)." (PMID 24641834, 2014). "So far, only the Hoxb7 gene expression is positively regulated by YY1 in tumor and transformed cell lines." (PMID 24705708, 2014). "Our findings provide a novel potential mechanism through which HOXB7 boosts tumor cell proliferation." (PMID 24853421, 2014). "In one previous study, we showed that most of the genes in the HOXB network are inactive in oral tissues, with the exception of HOXB2, HOXB7 and HOXB13, and that the misexpression of HOXB7 in OSCCs leads to increased tumor cell proliferation." (PMID 22498108, 2012). "YY1 can also impact senescence by regulating p16INK4a, and can increase HoxB7 expression directly involved in tumor progression." (PMID 22292011, 2012). "While several Hox proteins act as tumor suppressors, HOXB7 is overexpressed in primary breast carcinoma and metastasis, and it stimulates tumor progression by promoting epithelial-mesenchymal transition." (PMID 21957483, 2011). "Additionally, HOXB2 and HOXB7 are highly expressed in C1, C2, and C6 subtypes, which also indicates that they play a role in promoting tumor progression." (PMID 39980564, 2025). "In vivo, HOXB7 knockdown suppressed tumor growth and ERK pathway activation." (PMID 41040515, 2025).
tumor (continued). "The activation of the TGF-beta signaling pathway dependent on HOXB7 leads to increased cell motility and invasiveness, while also recruiting and activating macrophages of the immune system, indicating that HOXB7 is a crucial hub for tumor cells to activate and exploit their own immune system." (PMID 39980564, 2025). "Furthermore, HOXB7 was identified as a pivotal factor in increasing basic fibroblast growth factor (bFGF) secretion within the tumor environment and in promoting the proliferation and differentiation of bone marrow mesenchymal progenitors." (PMID 41040515, 2025). "The elevated expression of HOXB-AS4 in HNSCC may play a role in tumor promotion by influencing the HOXB7 gene located on the same chromosome, thereby activating the phosphorylation of AKT." (PMID 40657360, 2025). "Nevertheless, optimization of HOXB7 siRNA concentration may be interesting for enhancing the RNAi effect and re-sensitize tumor cells to TMX." (PMID 39458966, 2024). "In the present study, a controlled tumor volume growth was observed after HOXB7 knockdown by HNP-siHOXB7 associated or not with TMX." (PMID 39458966, 2024). "HOXB7, which belongs to class I homeobox genes, is involved in tumor progression and tumorigenesis." (PMID 37534217, 2023). "Interestingly, HOXB7 is functionally involved in tumor cell growth promotion through the direct transactivation of FGF2, which is also part of our 28-gene signature." (PMID 37445737, 2023). "Previous studies have proved that HOXB7 activation may be a functional bridge between the homeobox gene and tumor progression." (PMID 35945754, 2022). "Besides, HOXB7 can also induce other genes to be directly or indirectly related to angiogenesis and tumor invasion." (PMID 35945754, 2022). "Keshet and colleagues suggested that the epigenetic silencing of tumor suppressor genes could occur randomly or through a targeted pathway initiated by an oncogene, which in our case might be HOXB7." (PMID 34680970, 2021). "In addition, the number of Ki67-positive cells in tumor samples derived from HOXB7 knockdown cells was significantly reduced compared to samples formed from control cells." (PMID 34303375, 2021). "Secondly, several studies supported that HOXB7 might play a role in promotion of multistep process of tumor formation and progression, including proliferation, invasion, migration, angiogenesis and the epithelial–mesenchymal transition (EMT)." (PMID 34303375, 2021). "It is clear that there was no obvious association between HOXB7 expression and patients’ age, drinking and heavy tobacco usage, tumor size and gender." (PMID 34303375, 2021). "HOXB7/13 can improve the invasion and metastatic potential of tumor cells." (PMID 34306077, 2021). "Moreover, there is strong evidence already that HOXB7 plays a dominant role in facilitating tumor progression in HNSCC." (PMID 34303375, 2021). "Moreover, HOXB7 RNAi-related silencing significantly inhibited the expression of CSCs related markers and reduced the ability of tumor spheres formation in HNSCC cells." (PMID 34303375, 2021). "However, an in vivo approach showed that HOXB7 overexpression alone is insufficient to induce tumor formation and had a dual role when co-overexpressed with HER2." (PMID 34063128, 2021). "Nonetheless, whether overexpression of HOXB7 is sufficient to reverse the tumor inhibitory effect of MAGI2-AS3 overexpression remains to be ascertained." (PMID 33330444, 2020). "Following euthanasia, the tumor tissues were excised, and their expression of HOXB7 was determined by RT-qPCR, which revealed that HOXB7 was inhibited in tumor tissues of mice treated with oe-MAGI2-AS3, while it was promoted following treatment with sh-MAGI2-AS3 (p < 0.05)." (PMID 33330444, 2020). "However, HOXB7 also has been reported to promote tumor progression in several other cancers as well as angiogenesis." (PMID 30664713, 2019).